BAG2 (BAG cochaperone 2)
Diseases named in the same sentence as BAG2 in open-access papers (continued):
Sharing a sentence is not in itself a finding about the gene and the disease.
gastric cancer (continued). "We found that the expression of BAG2 in gastric cancer was significantly higher than that in normal gastric mucosa (P < 0.01), and the expression of BAG2 in diffuse gastric cancer was higher than that in intestinal adenocarcinoma." (PMID 32082999, 2020). "As for tumor pathology, the prognosis of BAG2 was analyzed by RNA samples from 354 cases of gastric cancer in The Cancer Genome Atlas." (PMID 32082999, 2020). "At the same time, we employed KM-Plotter database to analyze the correlation between the high/low expression of BAG2 and the clinicopathological characteristics of patients with gastric cancer." (PMID 32082999, 2020). "Simultaneously, we preliminarily confirmed the high expression of BAG2 in gastric cancer cell lines and its low expression in gastric mucosa cell line (GES1), which laid a foundation for further study." (PMID 32082999, 2020). "Using EdU reagent and Annexin V-FITC/PI cell apoptosis kit, we found that the proliferation ability of gastric cancer cells was markedly inhibited, and the apoptotic cells were significantly increased in BAG2 knockdown cells." (PMID 32082999, 2020). "Functional experiments revealed that BAG2 knockdown in gastric cancer cells inhibited the proliferation, invasion and migration of cells through AKT/mTOR and extracellular regulated kinase (ERK) pathways." (PMID 32082999, 2020). "Here, we reported that BAG2 was highly expressed in gastric cancer cell lines and tissues, indicating poor prognosis." (PMID 32082999, 2020). "In our study of the biological function of BAG2 in gastric cancer cells, we found an increase in apoptotic cells, the proliferation and migration of gastric cancer cells were significantly inhibited after BAG2 knockdown." (PMID 32082999, 2020). "Then we analyzed cell viability and proliferation of BAG2 knockdown gastric cancer cells using Cell Counting Kit-8 (CCK8) and colony formation assay, respectively." (PMID 32082999, 2020). "Results showed that the expression of BAG2 in GES1 was significantly lower than that in various gastric cancer cell lines." (PMID 32082999, 2020). "Furthermore, immunofluorescence co-localization analysis revealed the presence of BAG-2/Hsp70/CHIP ternary complexes in gastric cancer cells." (PMID 40755756, 2025). "Consequently, these results collectively suggest that the BAG2/CHIP axis promotes apoptosis in gastric cancer cells by impeding apoptosome assembly." (PMID 40755756, 2025). "In summary, the present study has yielded evidence that lends support to the hypothesis of BAG2 upregulation in gastric cancer tissues, as well as its moderate correlation with HSP70 expression." (PMID 40755756, 2025). "To this end, we employed a KO assay to deplete BAG2 expression in gastric cancer cells." (PMID 40755756, 2025). "Furthermore, our study identified BAG2 as a key gene that promotes the malignant progression of gastric cancer through the apoptotic pathway." (PMID 40755756, 2025). "It was determined that BAG2 is highly expressed in gastric cancer." (PMID 40755756, 2025). "Subsequently, we sought to determine whether the function of BAG2 in gastric cancer progression is mediated through the inhibition of ubiquitination and degradation of HSP70." (PMID 40755756, 2025). "In gastric cancer cells with high expression of BAG2, the process of apoptotic vesicle assembly may be optimized as the stability of HSP70 is enhanced." (PMID 40755756, 2025). "Furthermore, the knockdown of BAG2 significantly inhibited the proliferation, invasion, and migration of gastric cancer cells." (PMID 40755756, 2025). "Furthermore, we found that the regulatory effects of BAG2 on the proliferation and apoptosis of gastric cancer cells were dependent on HSP70." (PMID 40755756, 2025). "An oncogenic function of BAG2 is also reported in gastric cancer and oral cancer." (PMID 34257542, 2021).
gastric cancer (continued). "Overexpression of BAG2 suggests that BAG2 might have a role in the development of early metastasis and the more aggressive disease progression seen in the diffuse subtype of gastric cancer." (PMID 34885041, 2021). "BAG2 can promote the metastasis and proliferation of gastric cancer." (PMID 33763357, 2021). "The results of DEPs showed that BAG2 was regulated by mitogen-activated protein kinase (MAPK) and other signaling pathways, and previous cell functional experiments showed that BAG2 knockdown could attenuate the proliferation of gastric cancer cells." (PMID 32082999, 2020). "We demonstrated that BAG2 is a more valuable prognostic indicator of gastric cancer." (PMID 32082999, 2020). "In addition, we also examined the influences of BAG2 on the invasion and migration of gastric cancer cells by Transwell chamber." (PMID 32082999, 2020). "In conclusion, it is suggested that the process of BAG2 promoting EMT in gastric cancer cells may be partially regulated by miR186." (PMID 32082999, 2020). "Therefore, it is important to further investigate the molecular mechanism of BAG2, playing these biological functions in gastric cancer." (PMID 32082999, 2020). "The results showed that knockdown of BAG2 could notably inhibit the invasion and migration of gastric cancer cells." (PMID 32082999, 2020). "Taken together, our findings may reveal the basic function of BAG2 and uncover a potential therapeutic target for gastric cancer." (PMID 32082999, 2020). "Currently, the role of BAG2 in gastric cancer remains elusive." (PMID 32082999, 2020). "Therefore, we hypothesized that BAG2 plays a key role as a driver in the proliferation, invasion, and migration of gastric cancer cells." (PMID 40755756, 2025). "However, a limited number of studies have concentrated on the expression of BAG2 in gastric cancer." (PMID 32082999, 2020). "In light of this, we investigated the effect of BAG2 on the invasion and migration of HGC-27 and AGS gastric cancer cells." (PMID 40755756, 2025). "The present study is pioneering in its identification of BAG2 as a pivotal regulator of the CHIP-HSP70 axis and a modulator of apoptosis in gastric cancer, thereby establishing it as an independent adverse prognostic factor." (PMID 40755756, 2025). "The candidate proteins BAG2, GREM1, OLFM4, TRIP6, and MAGE-A9, were shown to be differentially expressed and validated using IHC in the diffuse and intestinal subtypes of gastric cancer." (PMID 34885041, 2021). "Overexpression of BAG2, GREM1, OLFM4, and TRIP6 in the diffuse subtype of gastric cancer on IHC as compared to the intestinal subtype suggests a role of these proteins in the pathogenesis and progression of the diffuse subtype." (PMID 34885041, 2021). "Next, we used the BAG2-specific siRNA to knock down BAG2 expression in HGC27 cells, and BAG2 knockdown on the biological behavior of gastric cancer cells was observed." (PMID 32082999, 2020). "Despite the evidence that inhibition of BAG2 decreased cancer cell proliferation, as highlighted above in oral and gastric cancer, there are no reports of small molecule inhibitors of BAG2." (PMID 34831344, 2021). "Conversely, in gastric cancer, the expression of CELF2, along with BAG2 (BAG Cochaperone 2), RBFOX2 (RNA Binding Fox-1 Homolog 20), and PTBP2 (Polypyrimidine Tract Binding Protein 2) splicing factors are associated with poor prognosis and alternative splicing events." (PMID 34681716, 2021). "In this study, we found that the expression of BAG2 in gastric cancer was significantly higher than that in normal gastric mucosa according to Oncomine and Human Protein Atlas databases." (PMID 32082999, 2020). "In addition, immunoprecipitation suggests that BAG2 can bind ERK1/2, and then promote the progression of gastric cancer." (PMID 32082999, 2020).
gastric cancer (continued). "Further investigation into the interplay between BAG2 and FGFR signaling in gastric cancer, along with the use of FIIN-2 or the development of more optimized dual-target/selective BAG2 inhibitors, could offer new insights and therapeutic opportunities for targeting apoptosis in gastric cancer cells." (PMID 40755756, 2025). "Although GREM1, BAG2, OLFM4, TRIP6 and MAGE-A9 have all been previously implicated in tumor progression and metastasis, they have not been linked to intestinal or diffuse subtypes of gastric cancer." (PMID 34885041, 2021). "In addition, immunoprecipitation suggested that BAG2 could bind to ERK1/2, thereby promoting the progression of gastric cancer." (PMID 32082999, 2020). "Our data showed that BAG2 knockdown might suppress intercellular EMT process by down-regulating the expression of N-cadherin, MMP9, Vimentin and Snail, thereby reducing invasion and migration of gastric cancer cells." (PMID 32082999, 2020). "At the same time, in DEPs detected by iTRAQ technology, we found that cell cycle and apoptosis regulatory protein 2 (CCAR2) decreased after BAG2 knockdown, suggesting that CCAR2 may act as a downstream factor of BAG2 to form miR186-BAG2-CCAR2 axis to regulate gastric cancer cell cycle and apoptosis." (PMID 32082999, 2020).
colorectal cancer (5 papers, 2015 to 2024). A primary or metastatic malignant neoplasm that affects the colon or rectum. "For instance, USP49 deubiquitinates and stabilizes Bcl‐2‐Associated Athanogene 2 (BAG2) which is a well‐known oncogenic protein that antagonizes apoptosis and enables adaptive response in colorectal cancer." (PMID 39497328, 2024). "Notably, upregulation of BAG2 is found in many types of cancer, including gastric cancer, glioma, hepatocellular carcinoma, oral cancer, and colorectal cancer, and is associated with the malignant progression of cancer 17-21." (PMID 36593950, 2023). "Whereas, ApoE-/- specifically activated 5 pathways (integrin, interferon, crosstalk between DC and NK cells, colorectal cancer metastasis, ephrin receptor) and suppressed 5 pathways (phenylalanine degradation IV, PCP, BAG2 and complement system) only in Ly6Clow MC." (PMID 34987524, 2021).
Parkinson disease (5 papers, 2016 to 2025). A progressive degenerative disorder of the central nervous system characterized by loss of dopamine producing neurons in the substantia nigra and the presence of Lewy bodies in the substantia nigra and locus coeruleus. "BAG2 has been shown to protect neurons against 1-methyl-4-phenylpyridinium-induced OxS in an in vitro cell model of Parkinson’s disease." (PMID 41300449, 2025). "Further investigation found that stabilization of PINK1 by BAG2 triggers Parkin-mediated mitophagy and protects neurons against 1-methyl-4-phenylpyridinium-induced oxidative stress in an in vitro cell model of Parkinson’s disease." (PMID 28536620, 2016). "In addition to a direct role in aggregate dissolution, BAG2 functions as a neuroprotective upstream regulator of the PINK1/PARKIN signaling pathway in an in vitro Parkinson’s disease model." (PMID 38928492, 2024). "In addition, BAG2 also interacts with PINK1, a Parkinson's disease-related protein, and directly binds and stabilizes both wild-type PINK1 and the R492X PINK1 mutant by decreasing their ubiquitination, which contributes to the pathogenesis of Parkinson's disease." (PMID 36593950, 2023).
glioma (4 papers, 2020 to 2025). A benign or malignant brain and spinal cord tumor that arises from glial cells (astrocytes, oligodendrocytes, ependymal cells). "For instance, LOXL1 and BAG2 proteins can interact in glioma cells, preventing BAG2-K186 ubiquitylation depending on LOXL1 enzymatic activity and stabilizing BAG2 to ultimately promote cell survival." (PMID 36593950, 2023). "Clinically, the patients with higher LOXL1 levels in their blood had much more abundant BAG2 protein levels in glioma tissues." (PMID 32424143, 2020). "The expression levels of LOXL1 and BAG2 are positively correlated (R = 0.42) in glioma and the correlation R value ranks fourth in all the 33 tumor types of TCGA." (PMID 32424143, 2020). "LOXL1 was found to prevent the ubiquitination of BAG2 in glioma and stabilize BAG2." (PMID 40426862, 2025). "Notably, patients with higher levels of LOXL1 in their blood had higher protein levels of BAG2 in their glioma tissues." (PMID 32424143, 2020). "In turn, BAG2 conferred glioma cell antiapoptotic activity to resist IR stress." (PMID 32424143, 2020). "Another study found that LOXL1 stabilizes the co-protein BAG2 by blocking K186 ubiquitination, which enables glioma cells to resist apoptosis under non-adherent conditions." (PMID 36825022, 2023). "In detail, LOXL1 is upregulated by the VEGFR-Src-CEBPA axis in suspended glioma cells, and LOXL1 and BAG2 proteins can interact in glioma cells, preventing BAG2-K186 ubiquitylation depending on LOXL1 enzymatic activity and stabilizing BAG2 to ultimately promote cell survival." (PMID 32424143, 2020). "In our study, LOXL1 stabilized BAG2 by blocking K186 ubiquitination, rendering glioma cells resistant to apoptosis in nonadherent conditions." (PMID 32424143, 2020).
Huntington disease (4 papers, 2022 to 2024). Huntington disease (HD) is a rare neurodegenerative disorder of the central nervous system characterized by unwanted choreatic movements, behavioral and psychiatric disturbances and dementia. "In contrast, in the time-series analysis, the top five ranking pathways include the BAG2 Signaling Pathway, Protein Ubiquitination Pathway, Huntington’s Disease Signaling, Inhibition of the ARE-mediated mRNA decay pathway, and Cellular response to Hypoxia." (PMID 38928492, 2024).
Alzheimer disease (3 papers, 2016 to 2023). A progressive, neurodegenerative disease characterized by loss of function and death of nerve cells in several areas of the brain leading to loss of cognitive function such as memory and language. "Additionally, they suggest a potential benefit conferred by the use of the polyphenol curcumin against Alzheimer’s disease-associated tau pathology, possibly through upregulating levels of the anti-tau co-chaperone BAG2." (PMID 28536620, 2016). "Based on the literature survey and Uniport database findings, this article focuses on the effects on the protein folding and degradation system and Alzheimer’s disease when the molecular network consisting of BAG2, HSC70, STUB1 and MAPT is dysregulated." (PMID 37251806, 2023). "In this study, the alterations in the expression of four genes were examined in individuals at various stages of Alzheimer’s disease to elucidate the role of BAG2, HSC70, STUB1 in folding and degradation of Tau in disease pathogenesis and progression." (PMID 37251806, 2023). "To further investigate the expression patterns and coordination of BAG2, STUB1, HSC70, and MAPT in Alzheimer’s disease patients, we performed a WGCNA analysis." (PMID 37251806, 2023). "We performed a Weighted Gene Co-expression Network Analysis (WGCNA) to investigate the expression patterns and coordination of BAG2, STUB1, HSC70, and MAPT in Alzheimer’s disease (AD) patients." (PMID 37251806, 2023).
cervical cancer (3 papers, 2023 to 2025). A primary or metastatic malignant neoplasm involving the cervix. "Specifically, RNA‐seq results revealed that BAG2 is associated with the expression of multiple ISGs in cervical cancer cells, which are vital for anti‐tumor immunity as an IFN‐induced gene." (PMID 40364789, 2025). "It was found that Bcl2-associated athanogene 2 (BAG2) suppressed the progression of cervical cancer by stabilizing STING." (PMID 41142804, 2025). "Clinically, there was a positive correlation between BAG2 and STING levels in cervical cancer, with low BAG2 expression strongly linked to advanced disease and poor prognosis." (PMID 41142804, 2025). "Collectively, these findings elucidate the molecular mechanism by which the BAG2‐STUB1 complex regulates STING homeostasis, underscoring BAG2's potential as a diagnostic biomarker and therapeutic target in cervical cancer." (PMID 40364789, 2025). "The results showed a significant positive association between BAG2 protein levels and overall cervical cancer survival in the HUteS168Su01 cohort (HR = 0.48, 95% CI = 0.24‐0.95, p = 0.0403)." (PMID 40364789, 2025). "We further investigated the association between BAG2 protein levels and clinicopathological features of cervical cancer." (PMID 40364789, 2025). "Low BAG2 expression is associated with poor prognosis of cervical cancer." (PMID 40364789, 2025). "We collected extensive data to investigate the relationship between BAG2 and clinical parameters in cervical cancer." (PMID 40364789, 2025). "That is, the tumor suppressor effect of the BAG2‐STING axis has broad applicability in cervical cancer cells under different HPV infection status." (PMID 40364789, 2025). "In the TCGA‐GTEx (normal: n = 13, tumor: n = 306) and Zhongnan hospital cohorts (paracancerous: n = 18, tumor: n = 18), BAG2 mRNA expression levels were usually down‐regulated in cervical cancer tissues." (PMID 40364789, 2025). "Given that BAG2 is involved in STING‐mediated regulation of type I interferon signaling in cervical cancer cells, we continued to explore the role of the BAG2‐STING axis in anti‐tumor activity." (PMID 40364789, 2025). "Functionally, enhanced BAG2 expression suppresses cervical cancer progression by activating the type I interferon pathway in a STING‐dependent manner." (PMID 40364789, 2025). "The results showed that BAG2 protein level was negatively correlated with clinical characteristics of cervical cancer, including Grade, Stage and N stage." (PMID 40364789, 2025). "The results indicated that BAG2 mRNA expression and protein levels were significantly lower in cervical cancer cell lines compared to HaCaT cell line." (PMID 40364789, 2025). "In terms of prognosis assessment, we investigated the predictive value of BAG2 in cervical cancer prognosis by Kaplan‐Meier survival analysis." (PMID 40364789, 2025). "In order to carry out additional research on the function of BAG2 in controlling the phenotype of cervical cancer, BAG2 was knocked down and overexpressed in cervical cancer cell lines." (PMID 40364789, 2025). "The mRNA and protein levels of BAG2 were evaluated in different cervical cancer cell lines (including C33A, CaSki, HeLa, and SiHa) and human non‐cancerous keratinocyte cell line (HaCaT)." (PMID 40364789, 2025). "Further, GSEA revealed that cervical cancer cells with BAG2 overexpression was significantly enriched in the type I interferon signaling pathway." (PMID 40364789, 2025). "To determine the combined effects of STING and BAG2 on cervical cancer cell growth and metastasis in vivo, we constructed control, BAG2, shSTING, and BAG2+shSTING stably transfected U14 cell line, and then verified the protein levels of BAG2 and STING by Western blot." (PMID 40364789, 2025).